MAML1 (mastermind like transcriptional coactivator 1)
Description:
Acts as a transcriptional coactivator for NOTCH proteins. Has been shown to amplify NOTCH-induced transcription of HES1. Enhances phosphorylation and proteolytic turnover of the NOTCH intracellular domain in the nucleus through interaction with CDK8. Binds to CREBBP/CBP which promotes nucleosome acetylation at NOTCH enhancers and activates transcription. Induces phosphorylation and localization of CREBBP to nuclear foci. Plays a role in hematopoietic development by regulating NOTCH-mediated lymphoid cell fate decisions.
Synonyms: Mam-1; KIAA0200; Mam1
Tractability: PROTAC: ubiquitination databases record sites on it.
Gene: Protein-coding gene on chromosome 5 (179,732,822 to 179,777,283, forward strand). Ensembl gene ENSG00000161021.
Subcellular location: Nucleus speckle
Subcellular location (Human Protein Atlas): Nucleoplasm
Pathways (Reactome):
Signal Transduction: NOTCH1 Intracellular Domain Regulates Transcription; NOTCH2 intracellular domain regulates transcription; NOTCH3 Intracellular Domain Regulates Transcription; NOTCH4 Intracellular Domain Regulates Transcription; Pre-NOTCH Transcription and Translation
Developmental Biology: Differentiation of naive CD4+ T cells to T helper 2 cells (Th2 cells); Formation of paraxial mesoderm; Regulation of gene expression in late stage (branching morphogenesis) pancreatic bud precursor cells
Disease: Constitutive Signaling by NOTCH1 HD+PEST Domain Mutants; Constitutive Signaling by NOTCH1 PEST Domain Mutants
Gene expression (Transcription): Notch-HLH transcription pathway; RUNX3 regulates NOTCH signaling
Gene Ontology:
Molecular function: peptide antigen binding; protein binding; protein kinase binding; transcription coactivator activity
Biological process: Notch signaling pathway; positive regulation of DNA-templated transcription; positive regulation of myotube differentiation; positive regulation of transcription by RNA polymerase II; protein phosphorylation; atrioventricular node cell development; atrioventricular node development; positive regulation of transcription of Notch receptor target; myoblast differentiation; positive regulation of muscle cell differentiation
Cellular component: CSL-Notch-Mastermind transcription factor complex; MAML1-RBP-Jkappa- ICN1 complex; nuclear speck; nucleoplasm; nucleus
Genetic constraint (gnomAD): Loss-of-function variants: 14 observed, 73.09 expected, observed/expected ratio (o/e) 0.19, 90% interval 0.13 to 0.3. The upper end of that interval is the gene's LOEUF score, 0.3, which puts it in group 1 of 6, group 1 being the genes least tolerant of losing a copy. Missense variants: 1,217 observed, 1,287.5 expected, observed/expected ratio (o/e) 0.95, 90% interval 0.9 to 0.99. Synonymous variants: 516 observed, 534.2 expected, observed/expected ratio (o/e) 0.97, 90% interval 0.9 to 1.04.
Homologues: Orthologues: chimpanzee MAML1 (99% identical), macaque MAML1 (98% identical), pig MAML1 (90% identical), dog MAML1 (88% identical), mouse Maml1 (87% identical), rat Maml1 (86% identical), rabbit MAML1 (80% identical), guinea pig MAML1 (62% identical), tropical clawed frog maml1 (55% identical), zebrafish maml1 (37% identical). Paralogues in human: MAML3 (36% identical), MAML2 (27% identical).
Diseases named in the same sentence as MAML1 in open-access papers:
MAML1 is named in the same sentence as 49 diseases in open-access papers, as found by Europe PMC text mining. Sharing a sentence is not in itself a finding about the gene and the disease. The quoted sentences say what the papers report.
breast cancer (9 papers, 2002 to 2024). A primary or metastatic malignant neoplasm involving the breast. "miR-133a-3p silencing caused MAML1 up-regulation, leading to the proliferation and metastasis of breast cancer cells both in vitro and in vivo." (PMID 31660998, 2019). "Epigenetic silencing of miR-133a-3p resulted in the abnormal upregulation of MAML1, which facilitated breast cancer metastasis both in vitro and in vivo." (PMID 39199304, 2024). "High MAML1 mRNA expression predicted poor prognosis in breast cancer patients (n = 2519, P < 0.005)." (PMID 31660998, 2019). "Next, we investigated the role of miR-133a-3p in mediating breast cancer cell metastasis in the mouse model by targeting MAML1." (PMID 31660998, 2019). "The epigenetic silencing of miR-133a-3p led to the aberrant up-regulation of MAML1, which facilitated the metastasis of breast cancer both in vitro and in vivo." (PMID 31660998, 2019). "Our data also revealed that MAML1 was up-regulated in breast cancer, and its high expression predicted poor clinical outcome for breast cancer patients." (PMID 31660998, 2019). "Consistently, MAML1 protein levels were higher in breast cancer cells than in normal breast cells, and had a negative correlation with the expression of miR-133a-3p." (PMID 31660998, 2019). "Mastermind-like transcriptional coactivator 1 (MAML1) was confirmed to be a target of miR-133a-3p involved in regulating breast cancer metastasis both in vitro and in vivo." (PMID 31660998, 2019). "In conclusion, DNA hypermethylation-induced silencing of miR-133a-3p facilitates breast cancer growth and metastasis by up-regulating MAML1, a target of miR-133a-3p." (PMID 31660998, 2019). "Collectively, these data demonstrated that miR-133a-3p silencing could promote the migration, invasion, proliferation, EMT process, and Notch signaling activation in breast cancer cells by targeting MAML1." (PMID 31660998, 2019). "Notably, we found that MAML1 protein levels were higher in all of the breast cancer tissues than their adjacent normal tissues." (PMID 31660998, 2019). "We next focused on studying whether silencing of miR-133a-3p facilitates breast cancer cell migration and invasion by up-regulating MAML1 expression and performed the rescue experiments." (PMID 31660998, 2019). "Taken together, these results indicated that MAML1 could be a direct target of miR-133a-3p in breast cancer, and might be corrected with poor outcomes in breast cancer patients." (PMID 31660998, 2019). "We believe that DNA hypermethylation of miR-133a-3p and the miR-133a-3p/MAML1/DNMT3A axis may provide novel therapeutic targets for the treatment of breast cancer, which is also of crucial significance for clinical prevention and diagnosis." (PMID 31660998, 2019). "Moreover, we observed that MAML1 overexpression slightly promoted the proliferation of breast cancer cells, and attenuated the inhibitory effect of miR-133a-3p on cell proliferation." (PMID 31660998, 2019). "By detecting DNMT1, DNMT3A, and DNMT3B mRNA levels, as well as DNMT3A protein levels in MAML1-overexpressing breast cancer cells, we confirmed that MAML1 could up-regulate DNMT3A expression." (PMID 31660998, 2019). "Therefore, targeting the positive feedback axis involving miR-133a-3p/MAML1/DNMT3A could be a potential therapeutic strategy for breast cancer." (PMID 39199304, 2024). "Therefore, to investigate whether miR-133a-3p expression was inversely correlated with MAML1 expression in breast cancer cells and clinical specimens, we measured MAML1 protein levels in 12 paired breast cancer tissues and adjacent normal tissues." (PMID 31660998, 2019). "Therefore, the miR-133a-3p/MAML1/DNMT3A positive feedback axis might provide potential targets for breast cancer therapy." (PMID 31660998, 2019).
breast cancer (continued). "In our study, we proposed that MAML1 was a target of miR-133a-3p and was required for Notch and EMT activation and breast cancer cell proliferation, migration and invasion both in vitro and in vivo." (PMID 31660998, 2019). "Recently, novel reports identify a role for MAML1 in T-cell acute lymphoblastic leukemia (T-ALL) in the axis MAML1-SP1-TRIM59, and in breast cancer through the miR-133a-3p/MAML1/DNMT3A positive feedback loop, indicating MAML1 as a potential therapeutic target for these pathological contexts." (PMID 33425921, 2020). "Taken together, our findings revealed a novel miR-133a-3p/MAML1/DNMT3A positive feedback loop in breast cancer cells, which may become a potential therapeutic target for breast cancer." (PMID 31660998, 2019). "To explore which type of DNA methyltransferases could be affected by MAML1, we first analyzed the correlation between MAML1 and common DNA methyltransferases (DNMT1, DNMT3A/B) in 1085 breast cancer tissues from the GEPIA public database." (PMID 31660998, 2019). "γ-secretase inhibitor (GSI) treatment inhibited the binding of NOTCH3/MAML1 complex to HES1 promoter, indicating that Notch pathway is active in these breast cancer cells and MAML1 might be a co-activator of Notch signaling in breast cancer." (PMID 20010940, 2010).
colon carcinoma (5 papers, 2017 to 2021). "Accordingly, MAML1-depletion induces cell death in colon carcinoma cells and a reduction of Cyclin D1 and c-Myc expression levels, suggesting a pivotal role for MAML1 in colon cancer progression." (PMID 33425921, 2020). "In fact, MAML1 is required for β-catenin–mediated transcription of specific target genes in vivo and is essential for colon carcinoma cell survival." (PMID 33425921, 2020).
atherosclerosis (3 papers, 2021 to 2023). A disease characterized by the build-up of fatty material and calcium deposition in the arterial wall resulting in partial or complete occlusion of the arterial lumen. "Therefore, further work which clarifies the exact relevance of the miR-133b–3p/MAML1 interaction in macrophages during atherosclerosis is required." (PMID 33483751, 2021). "In macrophages, miR-133b-3p modulates the expression of mastermind-like protein 1 (MAML1), which could serve as a proatherosclerotic factor, followed by the regulation of the NOTCH signaling pathway, which contributes to the plaque leukocyte influx and atherosclerosis progression." (PMID 37259293, 2023).
squamous cell carcinoma (3 papers, 2017 to 2023). A carcinoma arising from squamous epithelial cells. "Several of the MAML1-directed E6 proteins in this study were isolated from papillomaviruses in association with squamous cell cancers: OaPV3, CPV2, CPV3, CPV7, FcaPV2, and McPV2." (PMID 29281732, 2017). "While these few papillomaviruses were associated with squamous cell cancers, most MAML1-targeting E6 proteins were not cancer-associated." (PMID 29281732, 2017). "Our results implicate E6 targeting of MAML1 in animal squamous cell carcinomas." (PMID 29281732, 2017).
cutaneous squamous cell carcinoma (2 papers, 2015 to 2017). "The expression of a specific inhibitor of the Notch transcription complex, dominant negative MAML1 (DN-MAML), in murine skin led to the development of cutaneous squamous cell carcinoma." (PMID 26176534, 2015). "Among the HPVs, Beta genera E6 proteins repress MAML1, but the consistent and continued expression of Beta or Gamma genus viral oncogenes in cutaneous squamous cell carcinomas has not been observed." (PMID 29281732, 2017).
esophageal squamous cell carcinoma (2 papers, 2020 to 2022). Esophageal squamous cell carcinoma (ESCC) is a type of esophageal carcinoma (EC) that can affect any part of the esophagus, but is usually located in the upper or middle third. "In addition, an aberrant expression of MAML1 is described in esophageal squamous cell carcinoma (ESCC), human HCC and in head and neck squamous cell carcinoma, where it correlates with the clinicopathological features of tumors, predicting poor prognosis." (PMID 33425921, 2020). "In this regard, mastermind-like 1 (MAML1), a molecule with few side effects, may be used for targeting CD44+ CSCs via repressing the canonical NOTCH pathway in esophageal squamous cell carcinoma (ESCC) patients." (PMID 35250573, 2022).
glioblastoma (2 papers, 2015 to 2020). The most malignant astrocytic tumor (WHO grade IV). "The colocalization of endogenous RND3 with NICD, CSL, and MAML1 were visualized in U251 glioblastoma cells by immunofluorescent staining." (PMID 26108681, 2015). "However, NICD, MAML1, and CSL protein levels were significantly decreased in U251 glioblastoma cells with RND3 overexpression." (PMID 26108681, 2015).
glioma (2 papers, 2015 to 2019). A benign or malignant brain and spinal cord tumor that arises from glial cells (astrocytes, oligodendrocytes, ependymal cells). "Seventeen genes represent active Notch signaling components, including NOTCH1, NOTCH3, HES1, MAML1, DLL-3, and JAG2, which are enriched in the proneural subtype of glioma stem cells." (PMID 26599017, 2015).
medulloblastoma (2 papers, 2017 to 2020). A malignant, invasive embryonal neoplasm arising from the cerebellum. "Moreover, in primary samples of SHh-driven medulloblastoma, the most frequent childhood brain tumor, MAML1 expression is higher when compared to other medulloblastoma subtypes or healthy cerebellum in in silico analysis." (PMID 33425921, 2020).
muscular dystrophies (2 papers, 2020 to 2022). "In MAML1-null mice, Shen et colleagues observe muscle defects with a decrease of myogenin that results in muscular dystrophy, with a failure of MyoD-induced myogenic differentiation in embryonic fibroblast." (PMID 33425921, 2020). "A study revealed that mice with a MAML1 targeted disruption exhibited severe muscular dystrophy." (PMID 36360227, 2022). "A better knowledge of the mechanisms involved in the MAML1 regulation may improve the therapeutic approach in muscular dystrophies." (PMID 33425921, 2020).
renal cell carcinoma (2 papers, 2012 to 2018). "MAML1 acts cooperatively with EGR1 to activate EGR1-regulated promoters, which could also have implications for the development of renal cell carcinoma." (PMID 30466390, 2018). "Our findings suggest MAML1 may be a component of the transcriptional networks which regulate EGR1 target genes during nephrogenesis and could also have implications for the development of renal cell carcinoma." (PMID 23029358, 2012).
viral myocarditis (2 papers, 2023). Myocarditis that is caused by an infection with a viral agent. "In another investigation, Li and colleagues discovered the controlling pathway of miR-133 released from BM-MSC-EXO on myocardial fibrosis and EMT in viral myocarditis (VMC) animal model by regulating mastermind-like 1 (MAML1)." (PMID 36690996, 2023).
Cerebral ischemia (1 paper, 2023). Restriction of arterial blood supply to the brain associated with insufficient oxygenation to support the metabolic requirements of the tissue. "For example, miR-193b-3p can alleviate focal cerebral ischemia and reperfusion injury in rats, regulate cartilage formation and chondrocyte metabolism by targeting HDAC3, and regulate hepatocyte apoptosis in selenium-deficient broilers by targeting MAML1." (PMID 37078747, 2023).
Duchenne muscular dystrophy (1 paper, 2021). Duchenne muscular dystrophy (DMD) is a neuromuscular disease characterized by rapidly progressive muscle weakness and wasting due to degeneration of skeletal, smooth and cardiac muscle. "The muscle-specific lncRNA (linc-MD1) associate with Duchenne muscular dystrophy (DMD) to control the expression of transcriptional factors mastermind-like protein 1 (MAML1) and MEF2C." (PMID 33568070, 2021).
endometrial adenocarcinoma (1 paper, 2021). "Ishikawa cells (endometrial adenocarcinoma cells) were used as a model to assess the functional consequences of MAML1 knockdown on epithelial cell adhesion." (PMID 33773601, 2021).
female infertility (1 paper, 2021). Diminished or absent ability of a female to achieve conception. "Understanding the mechanism of action of MAML1 in the endometrium may uncover novel targets for therapies to treat female infertility and key pathways indicating the optimal time for embryo transfers to improve IVF success." (PMID 33773601, 2021).
ovarian carcinoma (1 paper, 2022). A malignant neoplasm originating from the surface ovarian epithelium. "In addition, NOTCH2, NOTCH3, DLL3, MAML1, and ADAM17 were determined as the five most relevant genes in ovarian cancer." (PMID 35136410, 2022).
papilloma (1 paper, 2017). A benign epithelial neoplasm that projects above the surrounding epithelial surface and consists of villous or arborescent outgrowths of fibrovascular stroma. "Furthermore, we demonstrate that the ability of MmuPV1 E6 to bind MAML1 is necessary for papilloma formation in experimentally infected mice." (PMID 28107544, 2017).
renal clear cell carcinoma (1 paper, 2012). "Bioinformatics assessment revealed a correlation between p300, EGR1 and MAML1 copy number and mRNA alterations in renal clear cell carcinoma and p300, EGR1 and MAML1 gene alterations were associated with increased overall survival." (PMID 23029358, 2012).
sensitization (1 paper, 2014). "SNPs in or near JAK2, CNOT6, MAML1, CD40, IL-4R, and IL-5RA genes were associated with allergic sensitization and SNPs in or near JAK1, JAK3, IL5RA, FCER1A, and ADAM33 genes were associated with cockroach sensitization." (PMID 25505553, 2014).
skin cancer (1 paper, 2017). "MmuPV1 E6 shares with the skin cancer-associated HPV8 E6 protein the capacity to inhibit Notch signaling by binding to MAML1, and MmuPV1-E6 mutants that are defective in MAML1 binding are defective in causing MmuPV1-induced papillomas." (PMID 29186900, 2017).
vascular tumors (1 paper, 2012). "By qRT-PCR, we have found a significant overexpression of MAML1 in AS with MAML1 amplification in comparison with AS without this aberration (P < 0.0001) and other vascular tumors (P < 0.0001)." (PMID 22383169, 2012).